VCAM1 (vascular cell adhesion molecule 1)
Diseases named in the same sentence as VCAM1 in open-access papers (continued):
Sharing a sentence is not in itself a finding about the gene and the disease.
tumor (continued). "Combination of sunitinib and anti-CD40 monoclonal antibody treatment increases the expression of ICAM-1 and VCAM-1 on tumor endothelial cells, enhancing intratumoral infiltration of CD8+ cytotoxic T cells." (PMID 39325128, 2024). "Considering the direct killing function of iNKT cells mediated by CD1d5,6, we explored the effect of blocking VCAM1-CD49d signaling on clearance of CD1d- and VCAM1-expressing tumor cells." (PMID 38332012, 2024). "MiR-126 promotes angiogenesis and the advancement of the tumor by lowering VCAM-1 levels, which also lessens the recruitment of inflammatory cells to the tumor site." (PMID 39199614, 2024). "We found that MC38 tumor cells inhibited motility of iNKT cells in vitro via a VCAM1 dependent manner, and that was restored by overexpression of CDC42 in iNKT cells." (PMID 38332012, 2024). "Its activation upregulates the expression of ICAM-1 and VCAM-1 on endothelial cells and reprograms tumor vasculature." (PMID 39325128, 2024). "Specifically, α4β1 expressed on tumor cells mediates their binding to lymphatic endothelial cells (LECs) via VCAM-1." (PMID 39274345, 2024). "Vascular cell adhesion protein 1(VCAM-1) expressed on the surface of cancer cells, can bind to α4 and β1 integrins overexpressed on the surface of macrophages, thereby achieving effective tumor targeting." (PMID 39189019, 2024). "Together, our data demonstrate that interfering with VCAM1-CD49d signaling enhances anti-tumor efficacy of iNKT cells irrespective the expression of CD1d or VCAM1 by tumor cells." (PMID 38332012, 2024). "Activated N1ICD is conductive to vascular cell adhesion molecule 1 (VCAM1) expression, recruitment of neutrophils, and intravasation of the tumor." (PMID 38892394, 2024). "Following pFUS, there was a 75% concordance for anti-tumor cytokines and inflammatory markers (including TNFα, IL-1a, IL-1b, IL-17, IL-6, and VCAM-1), indicating a TME shift toward a hot TME." (PMID 38543305, 2024). "We then knocked down Vcam1 in MC38-mCherry tumor cells to evaluate its effects on iNKT cell behavior." (PMID 38332012, 2024). "In fact, VCAM1 has been suggested as a factor in estimating poor patient prognosis and can promote tumor metastasis by inducing EMT in cancer." (PMID 38790973, 2024). "Even so, ICAM-1 and VCAM-1 expression is a double-edged sword for tumor cells because the innate immune system can prevent tumor cells from spreading though physical contact-mediated mechanisms." (PMID 38786066, 2024). "Blocking VCAM1-CD49d signaling improves motility and activation of intratumoral iNKT cells, and consequently augments their anti-tumor function." (PMID 38332012, 2024). "In fact, T-cell-mediated tumor rejection is inhibited by blocking T-cell binding to either VCAM-1 or ICAM-1 on endothelial cells." (PMID 39596815, 2024). "After washing with PBS, nearly all tumor cells were surrounded by AMDs, suggesting AMDs can bind VCAM‐1 positive cells." (PMID 38484186, 2024). "Macrophages and VCAM1 molecule in tumors respectively inhibit tumor infiltration and intratumoral motility of iNKT cells." (PMID 38332012, 2024). "VCAM-1 plays a crucial role in angiogenesis, leukocyte adhesion at inflamed tissues, and tumor sites, indicating its involvement in facilitating metastasis." (PMID 39286634, 2024). "We found that knockdown of Vcam1 in MC38-mCherry tumor cells improved infiltration of GFP+ transferred iNKT cells into tumors." (PMID 38332012, 2024). "We found that anti-VCAM1 antibody treatment and anti-CD49d antibody treatment significantly enhanced anti-tumor efficacy of iNKT cells in B16F10 tumor models." (PMID 38332012, 2024). "Downstream, co-targeting of additional biomarkers alongside VCAM-1 has the potential to provide a more nuanced view of tumour biology and the microenvironment." (PMID 39000268, 2024).
tumor (continued). "Hypoxia within the TME seems to play a pivotal role in impairing the expression of both VCAM-1 and of diverse adhesion molecules such as E-selectin, P-selectin, and ICAM-1 on the surface of tumor cells or tumor-associated cells." (PMID 39596815, 2024). "Overexpression of VCAM-1 results in lung or bone metastasis via recruitment of monocytes and macrophages and formation of a complex that promotes evasion of circulating tumor cells from immune attack and facilitates transendothelial migration." (PMID 39160581, 2024). "After entering tumors, VCAM1 in tumors, not limited to tumor cells, confines the motility of iNKT cells." (PMID 38332012, 2024). "Upregulation of VCAM-1 on endothelial cells of the tumor vasculature has been achieved upon the development of CAR T cells against VEGFR2." (PMID 39596815, 2024). "Both LFA-1/ICAM-1 and VLA-4/VCAM-1 interactions are critical for the extravasation and infiltration of recruited NK cells to the tumor." (PMID 38671750, 2024). "STING activation synergizes with VEGF receptor 2 (VEGFR-2) blockade, leading to normalization of the tumor vasculature, upregulation of VCAM-1 and ICAM-1, and regression of immunotherapy-resistant tumors." (PMID 39035739, 2024). "Another molecule likely to play a key role in monocyte recruitment to HCC tumours is the classical adhesion molecule, vascular cell adhesion molecule (VCAM)-1." (PMID 39684877, 2024). "As such, inhibition of PAK4 reduces expression of Slug and Zeb-1, upregulating expression of VCAM-1 and Claudin-14 in tumor ECs, which eventually enhances T cell adhesion and improves CAR T cell immunotherapy." (PMID 38580870, 2024). "VCAM-1 directs the adherence of MSCs to endothelial cells of tumor blood vessels which helps penetration and accumulation of MSCs at tumor sites." (PMID 39088082, 2024). "Next, we measured expression patterns of VCAM1 in tumors, and found that MC38 tumor cells expressed highest level of VCAM1, followed by monocytes, whereas DCs and particularly macrophages expressed low VCAM1." (PMID 38332012, 2024). "Nitric oxide (NO) affects leukocyte recruitment reducing tumor endothelial cell expression of adhesion molecules (E-selectin, VCAM-1, and ICAM-1) and pro-inflammatory cytokines." (PMID 39325128, 2024). "On the other hand, tumor VCAM-1 can promote cancer metastasis by recruiting monocytes to metastatic sites." (PMID 38786066, 2024). "Our study proposes a combinational immunotherapy with iNKT cell transfer and VCAM1/CD49d antibody treatment, irrespective the VCAM1 expression and CD1d expression by tumor cells." (PMID 38332012, 2024). "Succinobucol NPs have a better bioavailability (13 fold), which amplifies their capacity to prevent tumour cell migration and vascular cell adhesion molecule-1 (VCAM-1) invasion." (PMID 39720730, 2024). "TNF-α induces the expression of vascular cell adhesion molecule-1 (VCAM-1), which has pro-angiogenic potential and is tightly associated with tumor angiogenesis and tumor cell invasion." (PMID 37686525, 2023). "LN3 T-ALL cells were co-cultured with tumor-associated myeloid cells in the presence of anti-ICAM-1 and/or anti-VCAM-1 blocking antibodies." (PMID 37805579, 2023). "In contrast to the nonresponders, responders showed a significant enrichment in VCAM1+ and VCAM1+STING+ TECs in the tumor bulk and at the tumor–stroma interface, respectively." (PMID 38009521, 2023). "Significant expression differences of VCAM1 on the mRNA and protein level between tumor and normal tissues were found in ccRCC patients." (PMID 37622107, 2023). "This signaling pathway facilitates the upregulation of integrin α4β1 on LECs, consequently attracting VCAM-1-expressing tumor cells." (PMID 37744339, 2023). "VCAM1 expression was more heterogeneous in iCCA patient tumors, but was also found predominantly in tumor cells close to the tumor border with pMFs accumulation." (PMID 36828890, 2023).
tumor (continued). "We found that, indeed, the ZsG+ DTCs in both liver and lung in 3-month allograft tumors were consistently Vcam1-negative while tumor cells in the overt lung metastases had high levels of Vcam1." (PMID 36828890, 2023). "We show that Vcam1 is upregulated in the tumor cells at the early phase of pMF-iCCA interaction while its level drops when tumor cells begin to disseminate." (PMID 36828890, 2023). "A previous study showed that tumor expression of VCAM1 represents a novel mechanism of immune evasion." (PMID 36718454, 2023). "Specifically, tumor-derived EVs enriched in α4β1 (VLA‐4) or α9β1 were internalized only by lymphatic endothelial cells (VCAM-1+) from the subcapsular and medullary sinuses of B16-F10 melanoma-bearing mouse draining lymph nodes." (PMID 37350937, 2023). "Presence of ICAM-1, VCAM-1 and E-selectins on LECs enables the interaction with integrins present on tumor cells, facilitating their adhesion and migration through the lymphatic endothelium, and thus enabling their entrance into LVs." (PMID 37744339, 2023). "Records from the TCGA dataset analysis revealed higher levels of ICAM‐1 and VCAM‐1 in tumour specimens compared with the normal specimens." (PMID 37082943, 2023). "ICAM-1 and VCAM-1 are involved in subsequent adhesion with leukocytes, and they play a role in tumor cells–ECs adhesion." (PMID 37124539, 2023). "We find that vascular cell adhesion molecule-1 (Vcam1) level is elevated in tumor cells in contact with pMFs but low in disseminated tumor cells both in vitro and in vivo." (PMID 36828890, 2023). "CAMs, including ICAM-1 and VCAM1, are involved in the interaction and recruitment of immune cells to tumor sites." (PMID 37627528, 2023). "A similar tendency was observed in the analysis of the final levels of these biomarkers, namely in the G1 group, where the median final VEGF-R2, VEGF-R3, and VCAM-1 serum concentrations were similar to those in the tumor grade G2 (p > 0.05)." (PMID 36979820, 2023). "Vcam1 IHC on 1-month PPTR allograft tumors confirmed that Vcam1+ cells were predominantly the tumor cells close to the border where pMFs accumulated." (PMID 36828890, 2023). "P-and E-selectins mediate the adhesion of tumor cells to the endothelium, while integrin and its interaction with VCAM-1 on tumor cells promote firm adhesion." (PMID 37815894, 2023). "Vascular cell adhesion molecule-1 (VCAM-1) is a cytokine-induced adhesion molecule which is highly expressed on the surface of tumor cells." (PMID 36839671, 2023). "Further deciphering the transcriptional trajectories of endothelial cells using PAGA, we found that IL13RA1+ E02 and VCAM1+ E06, two major endothelial cell clusters in tumor tissues, exhibited unique features." (PMID 37488416, 2023). "S-Nitrosylation in the endothelium activates pathways that enhance VCAM-1 surface localization to promote binding of leukocytes and extravasation of tumor cells leading to metastasis." (PMID 37773178, 2023). "Our results show that B1R OE stimulated the expression of ICAM-1 and VCAM-1—adhesion molecules—thus promoting the migration and attachment of myeloid cells, particularly monocytes, to tumor cells." (PMID 37627528, 2023). "Macrophages can accumulate in the tumor microenvironment owing to some adhesion molecules and specific receptors, such as intercellular adhesion molecule-1, C-C chemokine receptor 2, and vascular cell adhesion molecule-1 (VCAM-1)." (PMID 37514008, 2023). "CCL5, VCAM1, and TLR2 have been demonstrated to be associated with the tumor immune microenvironment and promote PCa cell metastasis." (PMID 37494663, 2023). "Researchers detected that VCAM-1 plays a vital role in the metastasis of tumor cells and can be a potential therapeutic target in tumor metastasis." (PMID 36839671, 2023). "It has been reported that the treatment of murine models with different types of cancers by anti-VCAM-1 led to thrombosis and tumor necrosis in those neoplasm regions." (PMID 37280670, 2023).
tumor (continued). "It has been reported that in the lung metastasis of tumor cells, the high expression of VCAM-1 on the surface of tumor cells plays a crucial role in the formation of lung metastasis colonies." (PMID 36839671, 2023). "The flow chamber test revealed a reduction in tumor cell adhesion on the VCAM-1 substrate coating the flow chamber." (PMID 37626702, 2023). "Soluble VCAM1 can be derived from endothelial cells, leukocytes and/or tumour cells via cleavage by metalloproteinases." (PMID 37568580, 2023). "The result coincided with a recent study, reporting that VCAM1 secreted by CAFs promoted the tumor growth through AKT and MAPK signaling." (PMID 38097680, 2023). "TAMs improve the interaction between α4-integrin and vascular cell adhesion molecule-1 (VCAM-1) on the tumor cells, so they can activate the PI3K/Akt pathway and protect the tumor cells against pro-apoptotic activities such as TRAIL." (PMID 38017494, 2023). "DOX/CAT@PLGA-M1 displayed a significantly higher uptake in 4T1 cells, because VCAM-1 in tumor cells interacted with specific integrin (α4 and β1), and thereby achieved tumor sites." (PMID 37765212, 2023). "Many studies have demonstrated that IL-6 and TNF-a enhance tumor cell adhesion and that this is associated with an increased expression of ICAM-1 and VCAM-1 by mesothelial cells." (PMID 38068319, 2023). "The expression of VCAM1 was higher in the tumor tissue both at mRNA and protein levels in ccRCC compared with normal tissue, and was significantly positively correlated with immune signatures and survival characteristics in ccRCC patients." (PMID 37622107, 2023). "The camouflage of macrophage cell membrane enabled the nanocatalysts to have immune evasion ability and recognize tumor endothelium cells and cancer cells via α4/VCAM-1 interaction, further promoting tumor chemotactic aggregation." (PMID 37627810, 2023). "Vcam1 facilitates tumor mass expansion in both liver and lung and restrains tumor cells dissemination." (PMID 36828890, 2023). "Taken together, these results reveal an interesting context-dependent and Vcam1-regulated growth and dissemination of iCCA tumor cells." (PMID 36828890, 2023). "Overall, our data indicate that S-nitrosylation in the endothelium activates pathways that enhance surface localization of VCAM-1 to promote binding of leukocyte and/or tumor cells and extravasation leading to metastasis." (PMID 37773178, 2023). "Two studies demonstrated that human umbilical vein endothelial cells cultured with conditioned tumor media underwent epigenetic modifications that resulted in reduced VCAM-1 and ICAM-1 expression." (PMID 36189308, 2022). "Of note, VCAM-1-expressing tumor cells had a survival advantage in metastatic sites usually rich in leukocytes, such as the lungs." (PMID 36294305, 2022). "The interaction of integrin α4β1 on the tumor cell membrane with the VCAM-1 on vascular endothelial cells is involved in metastasis." (PMID 35739492, 2022). "ICAM-1 and VCAM-1 have been found to be deregulated in tumor EC, possibly due to the high expression of VEGFA." (PMID 35216427, 2022). "Doxorubicin-loaded PLGA nanoparticles were coated with monocyte-derived vesicles to achieve tumor targeting through the interaction of α4β1 integrin with VCAM-1." (PMID 35874757, 2022). "NF-kappa B can significantly promote tumor metastasis and the expression of tumor metastasis-related gene VCAM-1." (PMID 35711811, 2022). "Targeted recognition can be achieved through interactions between the abundant α4 and β1 integrin proteins on the macrophage surface with the highly expressed vascular cell adhesion molecule VCAM-1 on tumour cells." (PMID 35931744, 2022). "Vascular cell adhesion molecule (VCAM)-1 mediates cell-to-cell interactions and can induce the expression of VCAM-1 in the inflammatory tumor microenvironment by high expression of IL-1β." (PMID 36225358, 2022).
tumor (continued). "NF-κB has a significant promoting effect on tumor metastasis, and it can promote the expression of tumor metastasis-related genes VCAM-1, MMP-9, etc.." (PMID 35378772, 2022). "The JAK/STAT pathway interacts with intercellular cell adhesion molecules (ICAM-1) and VCAM-1 to promote tumor progression." (PMID 36035183, 2022). "This promotes MAMPC retention at the metastatic site by enhancing their physical interaction with tumor cells through VCAM1." (PMID 36077870, 2022). "VCAM-1 and ICAM-1 were highly expressed in sparse LEDs-PDT treated tumor tissues and were associated tumor angiogenesis, which in turn lead to poor tumor suppression." (PMID 36591528, 2022). "VEGF promotes, whereas bFGF inhibits, the adhesion of leukocytes via ICAM1 and VCAM1 to the tumour endothelial cells." (PMID 36077754, 2022). "Co-transplantation of VCAM-1-knockdown 3T3 fibroblasts with 4T1 cells into BALB/c mice resulted in markedly reduced tumor growth with significantly increased tumor-infiltrating T-cells, compared to co-transplanting control 3T3 fibroblasts with 4T1 cells." (PMID 35832090, 2022). "TNFα can potentially act as an angiogenic stimulus, which leads to distinct cell communication in the tumor microenvironment, inducing VCAM-1 expression." (PMID 36290384, 2022). "VCAM-1 on endothelial cells has the capacity to capture tumor cells, hinting at a mechanism for metastatic spread." (PMID 36290384, 2022). "Where VCAM-1 expression was visible further from the tumor border, adjacent sections stained for tumor-specific markers often revealed isolated tumor cells or tumor clusters nearby." (PMID 35312755, 2022). "Intracellular adhesion molecule 1 (ICAM1) and vascular cell adhesion molecule 1 (VCAM1) are dramatically reduced in tumor vessels determining a critical obstacle for T cells extravasation." (PMID 39086964, 2022). "Further, TNFα-treatment in BCSCs induced a pre-metastatic niche through breast-liver organ crosstalk by inducing vascular cell adhesion molecule-1 (VCAM-1) enriched neovasculogenesis in the liver of tumor-bearing mice." (PMID 36290384, 2022). "Subsequent, histologic analysis of the U87MG tumors demonstrated specific binding of VCAM-MPIO on VCAM-1–expressing vessels in proximity to the edge of the tumor." (PMID 35312755, 2022). "Here, we have shown that endothelial expression of VCAM-1 is upregulated in close proximity to the tumor and, particularly, at the tumor-brain interface." (PMID 35312755, 2022). "Taken together, these findings suggest that VCAM-1-mediated linkage to EC is required for TAPLT to confer protection of EC against tumor-induced permeation and angiogenesis, thereby resisting tumor extravasation and metastasis." (PMID 35408794, 2022). "In the ROC curve analysis, addition of VCAM-1 to the reference model comprising age, sex, and clinical tumor stage improved its discriminatory ability to predict LNM (+5.8 %; p < 0.001), ≥pT3 disease (+2.0 %; p = 0.008), and NOCD (+4.4 %; p < 0.001)." (PMID 35347517, 2022). "Histopathological staining (HE, TUNEL, Ki-67, VCAM-1, and ICAM-1) was used to determine the mechanism of tumor suppression caused by PDT with different light fields." (PMID 36591528, 2022). "Consistently, we here found that blocking FGFR signaling pathway markedly down-regulated VCAM-1 expression in CAFs, which was involved in the anti-tumor immunity by FGFR blockade." (PMID 35832090, 2022). "VCAM-1 was reported to be expressed on the surface of various cells such as macrophages, dendritic cells, fibroblasts, and tumor cells 22, In this study, we showed that VCAM-1 is relatively high expressed on CAFs in TME." (PMID 35832090, 2022). "Endothelial cells secrete a series of adherent molecules, such as E-selectin, VCAM-1, etc., to increase the adhesion of tumor cells with endothelial cells, and further promote tumor metastasis." (PMID 36466812, 2022).